CDK4 (cyclin dependent kinase 4)
Diseases named in the same sentence as CDK4 in open-access papers (continued):
Sharing a sentence is not in itself a finding about the gene and the disease.
liposarcoma (continued). "MDM2 and CDK4 were already familiar as important factors in the pathological diagnosis of liposarcoma, but as MDM2- or CDK4-targeted drugs were investigated, their efficacies against STS (especially liposarcomas) were also evaluated." (PMID 31963219, 2020). "Several protein kinases have been found to be overexpressed or highly activated in liposarcoma, including the proto-oncogenes phosphatidylinositol 3-kinase (PI3K)/AKT, cyclin-dependent kinase 4 (CDK4), and CDK11." (PMID 29568347, 2018). "Specifically, hMSCs that differentiated towards adipocytes or osteoblasts harbor CDK4 and MDM2 amplifications both of which frequently occur in osteosarcoma and liposarcoma that are both of same cell origin." (PMID 29416732, 2018). "It is known that virtually all WD and DD liposarcomas have MDM2 amplification and close to 90% have CDK4 amplification and this is felt to be an early event in the pathogenesis of these tumors." (PMID 29731991, 2018). "The expression of two inhibitors of Cdk4, Cdkn2a and Cdkn2b, was significantly increased, as a late event, present only in DAKO liposarcomas." (PMID 28459858, 2017). "This has previously been observed in dedifferentiated liposarcoma and even found to be co-expressed with MDM2 and CDK4." (PMID 28424409, 2017). "Amplification of cyclin-dependent kinase 4 (CDK4) and murine double minute 2 (MDM2) occurs in well-differentiated and dedifferentiated liposarcomas, as does down-regulation of PTEN." (PMID 28459858, 2017). "Immunohistochemistry for CDK4, MDM2, and p16 expression aids in the differential diagnosis of well-differentiated and dedifferentiated liposarcoma from other adipocytic neoplasms." (PMID 28856628, 2017). "Based on these as well as mathematic modeling, we have carried out a successful preclinical study using CDK4 and IGF1R inhibitors in liposarcoma." (PMID 26887042, 2016). "FOXM1 is elevated in de-differentiated liposarcoma and as FOXM1 is activated by progressive phosphorylation the relationship between palbociclib, CDK4 and FOXM1 in liposarcoma merits future research." (PMID 27074562, 2016). "CDK4 is located on the band q13 of chromosome 12, and this region contains MDM2, which is often amplified together in a variety of sarcomas such as liposarcoma, and rhabdomyosarcoma." (PMID 26992220, 2016). "Among the amplified and overexpressed genes were MDM2, CDK4 and HMGA2, all well-known amplified targets in liposarcoma." (PMID 27409346, 2016). "Another CDK4 inhibitor PD0332991, which can significantly suppress proliferation of hepatoma cells, has been evaluated in a clinical phase II study of liposarcomas." (PMID 27708221, 2016). "Based on this study as well as mathematical modeling we have carried out a preclinical study successfully by using CDK4 and IGF1R inhibitors in liposarcoma." (PMID 26887042, 2016). "In equivocal cases, MDM2 and CDK4 assessment by immunohistochemistry and/or molecular techniques (FISH) are helpful to exclude liposarcoma." (PMID 28078155, 2016). "CDK4 amplification is correlated with a significantly poorer progression-free survival (PFS) and disease-free survival of liposarcoma." (PMID 26528855, 2015). "The dedifferentiated liposarcoma can have prominent inflammatory myofibroblastic tumor-like features with expressions of MDM2 and CDK4 for identification." (PMID 25945274, 2015). "The most evidence, to date, demonstrates an oncogenic role in dedifferentiated liposarcoma, like the atypical lipomatous tumor/well-differentiated liposarcoma, for MDM2, CDK4, HMGA2, and TSPAN31 (SAS)." (PMID 25713799, 2015). "Expression of STAT6 in ca. 10% of dedifferentiated liposarcomas is based on amplification of the corresponding gene located in proximity to MDM2 and CDK4." (PMID 25432794, 2014). "In recent reports, it has been shown that dedifferentiated liposarcoma can have prominent inflammatory myofibroblastic tumor-like features with expressions of MDM2 and CDK4 for identification." (PMID 25022487, 2014).
liposarcoma (continued). "Most karyotypically complex liposarcomas have amplification of the 12q14 chromosome region that includes MDM2 and CDK4 gene." (PMID 25238053, 2014). "Their pattern was similar to an analysis of 38 well-differentiated/dedifferentiated liposarcomas which revealed overexpression of both HMGA2 and MDM2 in all cases, but with an inconsistent amplification of CDK4 in 13% of cases." (PMID 23766666, 2013). "There are two other cancers, dedifferentiated liposarcomas and lung adenocarcinomas that also show MDM2/CDK4 co-amplification in 90% and 4% of cases respectively." (PMID 24261984, 2013). "Most dedifferentiated liposarcomas are characterized by amplifications of MDM2 and CDK4 as part of the 12q amplicons involved in the formation of ring-chromosomes." (PMID 17359542, 2007). "Immunohistochemistry showed positivity for CDK4 and MDM2, and fluorescence in situ hybridization confirmed MDM2 amplification, leading to a diagnosis of atypical lipomatous tumor/well‐differentiated liposarcoma." (PMID 40416586, 2026). "CDK4 and MDM2 gene amplifications were identified in liposarcoma and osteosarcoma." (PMID 41562936, 2026). "Furthermore, we believe that MDM2/CDK4 immunohistochemistry and FISH assay for MDM2 amplification are valuable tools for conclusively ruling out well-differentiated liposarcoma (WDLPS), particularly in diagnostically challenging cases." (PMID 41356165, 2025). "The majority of dedifferentiated liposarcomas show amplification of MDM2 and CDK4." (PMID 40002892, 2025). "Intriguingly, p16 overexpression was similarly noted in liposarcomas lacking RB1 alterations but harboring ecDNA-based CDK4 amplification." (PMID 39185963, 2025). "The needle biopsy specimen showed scattered CDK4‐positive cells in the background of the lymphoma cells and sporadic MDM2 signal amplification on fluorescence in situ hybridization, suggesting mixed well‐differentiated liposarcoma (WDL)." (PMID 39894788, 2025). "Fluorescence in situ hybridization for MDM2 amplification can be used to differentiate atypical/highly differentiated liposarcoma and dedifferentiated liposarcoma from PMPF, while CDK4 gene amplification helps to differentiate atypical/highly differentiated liposarcoma from PMPF." (PMID 40308488, 2025). "Genetic findings in ESOS are nonspecific; approximately 10–20% of cases exhibit MDM2 and CDK4 amplification, typically seen in dedifferentiated liposarcoma." (PMID 40308507, 2025). "For instance, well-differentiated liposarcoma (WDLPS) and dedifferentiated liposarcoma (DDLPS) are characterized by gene amplification of murine double minute-2 (MDM2) and cyclin dependent kinase 4 (CDK4)." (PMID 40909947, 2025). "Additionally, the amplification of MDM2 or CDK4, detected through FISH, can aid in the diagnosis of liposarcoma." (PMID 40797498, 2025). "Herein, we describe the case of a 91-year-old woman diagnosed with ovarian mucinous cystadenoma with a well-differentiated liposarcoma mural nodule, based on histological morphology, immunohistochemical examination, and MDM2/CDK4 fluorescence in situ hybridization (FISH) testing." (PMID 39220649, 2024). "It is important to note that many liposarcomas and other sarcomas, including intimal sarcoma with MDM2/CDK4 amplification, may exhibit cytoplasmic and/or nuclear expression of STAT6 without necessarily indicating a solitary fibrous tumor." (PMID 38275873, 2024). "This particularly applies to well-differentiated or dedifferentiated liposarcomas, which might not only benefit from MDM2 or CDK4 inhibitors, but also from anti-GLI1 therapies." (PMID 38275873, 2024). "Regarding other possible differential diagnoses, a lack of mouse double minute 2 homolog and CDK4 expression excludes liposarcoma." (PMID 38542211, 2024).
liposarcoma (continued). "Combining the histological morphology, immunohistochemistry, and MDM2/CDK4 FISH test results, we diagnosed the patient with ovarian mucinous cystadenoma with a mural nodule of well-differentiated liposarcoma, International Federation of Gynecology and Obstetrics (FIGO) stage IA." (PMID 39220649, 2024). "Similarly, we observed that CDK4 immunopositivity, in malignant cases (ALT/WDLS and liposarcomas), must be over 25% of the nuclei (p < 0.001)." (PMID 38132190, 2023). "Simultaneously, cell lines derived from dedifferentiated liposarcomas carrying 12q13-15 region amplification (including MDM2 and CDK4 genes) represent an excellent preclinical model for the study of well-differentiated (WDLPS) and dedifferentiated (DDLPS) liposarcoma development and proliferation." (PMID 38002306, 2023). "Targeting CDK4 seemed particularly attractive for WDLPS and DDLPS, in which it has a specific clinical and biological significance, with respect to MDM2 amplified-only liposarcomas." (PMID 36741019, 2023). "Of note, a small subset of dedifferentiated liposarcomas (DDLPS) may show expression since the STAT6 gene may be co-amplified with its neighboring genes, MDM2 and CDK4." (PMID 33921435, 2021). "The dedifferentiated liposarcomas are characterized by mouse double minute 2 (MDM2) and cyclin-dependent kinase 4 (CDK4) amplifications, and the CDK4 inhibitor, abemaciclib, is currently under investigation; an encouraging 12-week PFS of 76% in a phase II nonrandomized trial has been reported." (PMID 34207243, 2021). "Excitingly, palbociclib and its relatives are showing great promise in clinical trials for other solid tumors, including another aggressive sarcoma, dedifferentiated liposarcoma (DDLPS), which frequently harbors amplification of CDK4 (NCT01209598, NCT02897375)." (PMID 33456709, 2021). "Immunohistochemically, the combination markers of cyclin-dependent kinase 4 (CDK4) and human murine double minute 2 (MDM2) were useful in the diagnosis of dedifferentiated liposarcoma, and there is strong correlation of marker expression with gene amplification status." (PMID 33422117, 2021). "Interestingly, similar effect was observed upon exposure to PARP inhibitor in case of liposarcoma and other tumors, however, upregulation of p21WAF1/CIP1 and proteosomal degradation of MDM2 were accompanied by downregulation of CDK4." (PMID 30734151, 2020). "MDM2 and CDK4 nuclear staining is not a characteristic of benign lipomatous tumors in well-differentiated and dedifferentiated liposarcomas; however, it should be noted that it is not encountered in myxoid and round cell pleomorphic liposarcomas." (PMID 31282548, 2020). "MDM2 inhibitors under investigation have demonstrated responses in early phase clinical trials in MDM2 amplified soft tissue sarcomas (with or without CDK4 co-amplification) such as liposarcoma and synovial sarcoma." (PMID 31480474, 2019). "The evidence regarding MDM2 inhibitors as a treatment for liposarcoma is limited to preclinical data and a phase I trial, but the double inhibition by MDM2 and CDK4 might be synergic, which would be worth evaluating." (PMID 29510588, 2018). "While previous studies have assessed the expression of CDK4 in some sarcoma types, including liposarcoma and Ewing’s sarcoma, none of these studies have assessed the expression of CDK4 in synovial sarcoma." (PMID 29670090, 2018). "Specifically, CDK4 and MDM2 were frequently amplified in liposarcoma and osteosarcoma." (PMID 29416732, 2018). "By contrast, liposarcomatous differentiation in PTs is not underpinned by amplification of the MDM2/CDK4 locus, which is a well‐characterized driver of well‐differentiated and dedifferentiated liposarcomas and frequently detected in uterine adenosarcomas." (PMID 28267263, 2017).
liposarcoma (continued). "In almost 90% of well- and dedifferentiated liposarcomas, an amplification of the 12q13-q22 gene region is present, as well as an overexpression of mouse double minute 2 homolog (MDM2) and cyclin dependent kinase 4 (CDK4), proteins characteristic of these liposarcoma subtypes." (PMID 28895916, 2017). "The proto-oncogenes CDK4 and MDM2 are both amplified in well-differentiated liposarcoma." (PMID 27074562, 2016). "While no specific chromosomal translocations have been identified in well differentiated/dedifferentiated liposarcomas, amplification of MDM2 and CDK4 is very frequent in these subtypes, and their identification may be useful diagnostically." (PMID 25927975, 2015). "The levels of CDK4 amplification were not different in DD liposarcomas, regardless of tumor recurrence status." (PMID 25121597, 2014). "WD and DD liposarcomas with no CDK4 amplification represent a distinct clinical subgroup with a lower recurrence rate and are more likely to be peripherally located." (PMID 25121597, 2014). "WD liposarcomas with recurrence after surgical resection had significantly higher levels of CDK4 amplification compared to those without recurrence (P = 0.041)." (PMID 25121597, 2014). "While MDM2 amplification and overexpression is present in most WD and DD liposarcomas, CDK4 amplification is absent in a small proportion of cases." (PMID 25121597, 2014). "The diagnosis of a well-differentiated liposarcoma was suspected but molecular cytogenetic analyses showed no MDM2 or CDK4 gene amplification on fluorescent in situ hybridization and the diagnosis of a benign lipoma was confirmed." (PMID 24363942, 2013). "In contrast, amplifications of Mdm2 and/or Cdk4 (which were additionally tested because of their frequent amplification in human sarcomas, most prominently liposarcomas) were rare (<5%; not shown)." (PMID 21533183, 2011). "Importantly, the absence of cytologic atypia, lipoblasts, and mitotic activity supports a diagnosis of lipoma and helps exclude atypical lipomatous tumor/well-differentiated liposarcoma, but when morphology is equivocal, ancillary MDM2/CDK4 testing is recommended." (PMID 41367444, 2025). "Amplification of MDM2 and positivity for CDK4 are more characteristic of well-differentiated liposarcomas in particular, and though a small percentage can be positive for STAT6, that marker is more specific for solitary fibrous tumors (SFTs) or dedifferentiated liposarcomas." (PMID 41141132, 2025). "Lipoblastoma is MDM2- and CDK4-negative, while liposarcoma is positive." (PMID 40151705, 2025). "However, neither giant cells nor lipoblasts were detected by histology and the lack of simultaneous CDK4- plus MDM2-amplification ruled out an atypical lipomatous tumor/well-differentiated liposarcoma." (PMID 38681749, 2024). "Similarly, well-differentiated/dedifferentiated liposarcomas and other neoplasms with MDM2/CDK4 amplification may also exhibit coamplification of GLI1." (PMID 38275873, 2024). "Hence, at this time the main utility of targeted sequencing in WD/DD liposarcoma patients using commercially available panels such as FM would be to identify patients for clinical trials testing agents that target the MDM2 and/or the CDK4 pathway." (PMID 29731991, 2018). "However, because that subtype is relatively indolent and easily curable with surgical resection, CDK4 inhibitors are not necessary for treatment of well differentiated liposarcoma." (PMID 27016421, 2016). "It has been suggested that CDK4 provides a selection advantage in well-differentiated liposarcoma and may contribute to transformation as CDK4 negative well-differentiated liposarcoma exhibit more favorable prognostic features." (PMID 25713799, 2015). "Since MDM2 and CDK4 amplifications are present in both well-differentiated and dedifferentiated liposarcoma, the presence of these amplifications as such are not triggers for dedifferentiation in liposarcomas." (PMID 25713799, 2015).
liposarcoma (continued). "ALT/WDL and dedifferentiated liposarcomas (DDL) most often have a supernumerary ring and giant marker chromosomes composed of amplified sequences from the 12q13-15 region, including the murine double-minute type 2 gene (MDM2) and the cyclin-dependent kinase 4 gene (CDK4)." (PMID 24965044, 2014). "Moreover, WD liposarcomas with recurrence after surgical resection had significantly higher levels of CDK4 amplification compared to those without recurrence and the degree of CDK4 amplification was an independent risk factor for recurrence of WD liposarcoma after complete excision." (PMID 25121597, 2014). "Finally, we confirmed the expected overexpression of some genes: KIT and ANO1/DOG1 in GISTs, MDM2 and CDK4 in non-myxoid/round cells liposarcomas, CALD1 and tropomyosin genes (TPM1, TPM2) in leiomyosarcomas, PDGFB in DFSPs, MUC1/EMA in synovial sarcomas, and CD34 in SFTs." (PMID 23734203, 2013). "However, MDM2 and CDK4 are not specific markers for liposarcoma." (PMID 23971887, 2013). "Histopathology confirmed benign lipomatosis with CDK4(+), MDM2(+), Ki-67 (+,2%), and negative MDM2 amplification on fluorescence in situ hybridization (FISH), arguing against well-differentiated liposarcoma." (PMID 41869673, 2026). "Unlike liposarcoma, lipomas contain mature adipocytes without atypia or lipoblasts, and lack molecular alterations such as MDM2 or CDK4 amplification." (PMID 41146960, 2025). "On the other hand, well-differentiated liposarcomas consist of atypical, hyperchromatic stromal cells and are negative for CD34 and positive for MDM2 and CDK4." (PMID 40777097, 2024). "ASPLTs show no MDM2 or CDK4 amplification, which distinguishes them from atypical lipomatous tumor (ALT)/well-differentiated liposarcomas (WDLPS), and dedifferentiated liposarcomas (DDLPS)." (PMID 36983010, 2023). "Although no typical well-differentiated liposarcoma component was observed, MDM2, CDK4 and P16 IHC staining were diffusely positive, and MDM2 gene amplification, identified by FISH, supported the diagnosis of DL." (PMID 36123846, 2022). "We first confirmed expression of CDK4 and MDM2 as established biomarkers of WDLPS and DDLPS and determined that both markers were highly expressed in the liposarcoma cell lines regardless of adipogenic potential when compared to normal HuASC primary cells." (PMID 35313831, 2022). "Negative staining of CDK4 and MDM2 ruled out well-differentiated liposarcoma and dedifferentiated liposarcoma." (PMID 34797454, 2021). "Although the case showed MDM2, CDK4, and DDR2 gene amplification, which were genetically similar to liposarcoma, upon microscopic examination, neither the primary nor the recurrent IMTs presented as liposarcoma." (PMID 32195970, 2020). "Dedifferentiated liposarcoma, which shows the similar morphology to SFT on microscopy, was differentiated because IHC for MDM2 and CDK4 was negative in the present case." (PMID 26337721, 2015). "The differential diagnosis for dedifferentiated liposarcoma and Rhabdoid tumor were dismissed by immunohistochemical analysis that showed negative staining for MDM2, CDK4, p16 and positive staining for BAF47(INI1)." (PMID 26208724, 2015). "We suggest that the presence or absence of a well-differentiated liposarcoma component and expressions of MDM2 and CDK4 should be considered in the diagnosis of IMTs and requires further research." (PMID 25022487, 2014). "Diagnosis of a well-differentiated liposarcoma was suspected and molecular cytogenetic analyses showed no MDM2 nor CDK4 gene amplification on fluorescent in situ hybridization." (PMID 23308321, 2012). "Dedifferentiated liposarcoma is a high-grade non-lipogenic sarcoma that arises in a background of a pre-existing well-differentiated liposarcoma, harbouring a genomic amplification in the 12q13–15 region constituting the MDM2, CDK4 and HMGA2 genes." (PMID 29621151, 2018).
liposarcoma (continued). "Therefore the presence or absence of a well-differentiated liposarcoma component and expression of MDM2 and CDK4 should be considered in the diagnosis of IMTs and requires further research." (PMID 25945274, 2015).